RAF1 (Raf-1 proto-oncogene, serine/threonine kinase)
Diseases named in the same sentence as RAF1 in open-access papers (continued):
Sharing a sentence is not in itself a finding about the gene and the disease.
tumor (continued). "We examined the potency of tumor-agnostic therapy for fusion-driven cancer, by assessing the effect of BRAF inhibitor in RAF1 fusion-driven cancer." (PMID 36033527, 2022). "Sorafenib exerts anti-tumor effects via inhibiting vascular endothelial growth factor receptor (VEGFR), Raf-1, B-Raf, and platelet-derived growth factor receptor (PDGFR)." (PMID 36189208, 2022). "By inhibition of the RAF1-MAPK (mitogen-activated protein kinase) pathway, RKIP acts as a beneficial tumour suppressor." (PMID 35203304, 2022). "Regorafenib inhibits multiple tyrosine kinases involved in tumor angiogenesis (VEGFR1-3, TIE2), oncogenic transformation (KIT, RET, RAF1, BRAF), and shaping tumor microenvironment (PDGFR, FGFR)." (PMID 34527573, 2021). "For instance, we have reported that KLF10 was phosphorylated by CDK2 and Raf-1 at Ser206 and Thr93, respectively, further affecting the role of KLF10 in tumor suppression." (PMID 34869587, 2021). "In this model, ablation of RAF1 or EGFR caused a delay of the formation of PDAC, whereas the concomitant knock-out of both RAF1 and EGFR genes completely suppressed tumour development." (PMID 33920182, 2021). "According to the research for the influence of RAF-MEK-ERK pathway in tumor growth, expressing dominant-negative MEK in tumor cells affects a reduction in endogenous Raf-1 and MEK-1 activity." (PMID 34830757, 2021). "Regorafenib is an oral multikinase inhibitor of several protein kinases, including kinases involved in tumor angiogenesis (VEGFRs 1–3), oncogenesis (KIT, RET, RAF1, BRAF, and BRAFV600E), and development of the tumor microenvironment (PDGFR and FGFR)." (PMID 33337518, 2021). "It inhibits VEGFR, Raf-1, B-Raf, platelet-derived growth factor receptor (PDGFR), c-KIT receptor, and p38 signaling pathways involved in angiogenesis and tumor proliferation." (PMID 33718121, 2020). "Conversely, regorafenib, a novel oral MKI, blocks several protein kinases involved in the tumor angiogenesis (VEGFR-1, -2, and -3), tumor growth (KIT, RET, RAF-1, and BRAF), and metastasis (PDGFR-β, FGFR1) of cancer cells." (PMID 32466169, 2020). "The phosphorylation of VEGFR-2 activates the Raf-1/MAPK/ERK signaling pathway, which will eventually lead to angiogenesis, enhanced vascular permeability, tumor proliferation and tumor migration." (PMID 32521825, 2020). "Sorafenib inhibits Raf‐1 which is expected to increase ASK1 and tumor cells chemosensitivity to doxorubicin." (PMID 32841541, 2020). "First, sorafenib directly inhibits tumor cell proliferation by targeting multiple kinases involved in the Ras/Raf/MEK/ERK signaling pathway, including Raf-1, B-Raf." (PMID 31750247, 2019). "In this study, based on our in vitro and in vivo results and literature data, we introduce a novel, comprehensive network of common tumor-related proteins, such as PD-1, MET, RAF1, STAT3, BCL2, or mTOR." (PMID 31681332, 2019). "The other main pathway was pathway in cancer, and the genes in this pathway can impact tumor cell proliferation (PPARG, RAF1), regulate hepatic glucose and lipid metabolism (FOXO1), and decrease the viability and invasiveness of HCC cells (RALA)." (PMID 31799078, 2019). "High expression of miR-497 has been shown to suppress MEK1, RAF1 and ERK1 proteins in HeLa cells, thus functioning as a tumor suppressor." (PMID 30399176, 2018). "Consistent with the in vitro studies, the positive stain of the proliferation and senescence markers and protein level of DEPP were increased accompanying with Raf1 and ERK activation in tumor tissues in the baicalin treatment group." (PMID 29440765, 2018). "Overexpression of DEPP distinctly increased the protein levels of p-Raf1, p-ERK and p16INK4A, and decreased the expression of pRb in tumor cells." (PMID 29440765, 2018).
tumor (continued). "Regorafenib is a different oral MKI that potently blocks multiple protein kinases involved in tumor angiogenesis (VEGFRs 1–3, TIE2), oncogenesis (KIT, RET, RAF-1, BRAF), metastasis (VEGFR3, PDGFR, fibroblast growth factor receptor), and tumor immunity (CSF1R)." (PMID 29291014, 2017). "PyMT activates Ras13, which can signal via its direct effector Raf-1 and the mitogen-activated protein kinase (MAPK) pathway to drive tumour cell growth." (PMID 28102194, 2017). "Many potential targets of miR-7 were reported to participate in some important signalling of tumor progression, such as targets EGFR, IRS-1, PAK-1, RAF-1, SATB1, and so on." (PMID 28239300, 2017). "Of all CNA gene gains and losses, the PI3K-Akt Pathway enlisted 264 genes of which RAF1 (16 times lost), ITGA9 (15 times lost) and LAMB2 (15 times lost) were abundantly affected in HRO G1 ccRCC tumour samples." (PMID 28486536, 2017). "We next analysed the state of signalling pathways connected to RAF1 and HCC development in tumour-bearing livers and in xenografts." (PMID 28000790, 2016). "Both models have revealed a tumour suppressor function of RAF1 in HCC, consistent with the reduced RAF1 expression in HCC patients." (PMID 28000790, 2016). "BCL2 BH4 domain also binds to calcineurin, CED-4, HIF-1α, c-Myc, paxillin, Raf-1, Ras and VDAC, promoting tumorigenesis or tumor survival and contributing to both anti-apoptosis and pro-tumorgenesis activities of BCL2." (PMID 27049723, 2016). "Increased expression of prohibitin and Raf-1 in 1459 co-cultures with malignant vesicles (HCT116 and 004CT Tumor) was validated with Western blotting." (PMID 26231887, 2015). "Protein expression of Raf-1 and MAPK, including their activation status, was analysed using immunohistochemistry in a database of 65 paired tumour specimens obtained before and after the development of CRPC and correlated with other members of the pathway." (PMID 21559022, 2011). "Significant correlations were observed between protein expression of Raf-1 and MAPK with the type 1 receptor tyrosine kinases, Her2 and epidermal growth factor receptor, as well as the transcription factor AP-1 in CRPC tumours." (PMID 21559022, 2011). "The Raf-1/MEK/ERK pathway has long been recognized for its role in tumor biology and specifically for its role in MTC tumor development." (PMID 20069043, 2009). "Araf ablation alone or combined with Raf1 did not affect tumor initiation, progression, or regression rates." (PMID 41650121, 2026). "Western blot analysis of tumor tissues showed that HOXB7 knockdown led to downregulation and decreased phosphorylation of several key components in the H-Ras/MEK/ERK signaling pathway, including H-Ras, RAF1, p-MEK, and p-ERK." (PMID 41040515, 2025). "The use of type I BRAF inhibitors is limited to patients with tumors harboring a BRAF V600E mutation due to the risk of paradoxical activation of the MAPK pathway and accelerated tumor growth if used in patients with tumors harboring a RAF fusion, such as those involving BRAF or CRAF/RAF1." (PMID 38291372, 2024). "Our results have indicated that both tumoral and non-tumoral cells in the tumor microenvironment can be responsible for the altered expression of RAF1 in GBM." (PMID 38655096, 2024). "Regorafenib is an oral multikinase receptor inhibitor that blocks tyrosine kinases active in angiogenesis (VEGFR1–3 and TIE2) and cancer growth (KIT, RET, RAF1, BRAF and BFRAFV600E), growth factors (FGFR and PDGFR), and tumor immunity promoters as the colony-stimulating factor 1 receptor (CSF1R)." (PMID 38473776, 2024). "In addition to luciferase, the combination (H3K-33 (85%)/H2K-CO2H) markedly reduced endogenous Raf-1 mRNA (23.1% of control, 76.9% inhibition) and oncoprotein similarly in an MDA-MB-231 tumor-mouse model." (PMID 39683699, 2024).
tumor (continued). "In addition, western blotting analysis further detected the phosphorylation levels of RAF1, MEK and ERK1/2 in 4 random xenograft tumours from the sh2 group and 4 random xenograft tumours from the scr group." (PMID 37037864, 2023). "Regorafenib is an oral inhibitor of several kinases involved in tumor angiogenesis (VEGFR1-3 and TIE2), oncogenesis (KIT, RET, RAF1, and BRAF), and in the interaction between tumor and microenvironment (PDGFR, FGFR), and tumor immunity (colony-stimulating factor 1 receptor [CSF1R])." (PMID 37071295, 2023). "Given the efficacy achieved in tumor therapy and the preliminary work in AMI, intervening in genes such as MAPK1 and RAF1 and modulating the MAPK cascade response may lead to new therapeutic options for AMI." (PMID 36238493, 2022). "Regorafenib is an oral tyrosine kinase inhibitor that blocks multiple protein kinase activities, including proteins involved in the regulation of oncogenesis (KIT, RET, RAF-1 and BRAF), tumour microenvironment (PDGFR and FGFR) and tumour angiogenesis (VEGFR1, 2 and 3 and TIE-2)." (PMID 35326702, 2022). "In addition, pharmacologic activation of both Notch1 and Raf-1 signaling in MTC cells reduces aberrant secretion of hormones and tumor cell proliferation, suggesting a tumor suppressive role for Notch1 signaling in this context." (PMID 33681228, 2021). "Analyzing the whole-blood expression signature of four growth factor-related genes (ARAF, BRAF, KRAS, and RAF-1) and four genes involved in metabolism (ATP6V1H, OAZ2, PANK2, and PLD3), combined with tumor grade, they were able to predict the efficacy of PRRT with an accuracy of 95%." (PMID 33809226, 2021). "However, for the KRASG12C tumor, LINCS analysis returned different drugs (NES < −3.6, P < 0.04), inhibitors of HSP70, GSK3β, and KRAS signal transducers BRAF and RAF1." (PMID 33712615, 2021). "Our previous studies indicated that Raf-1 phosphorylated KLF10 leading to its destabilization by binding to peptidyl-prolyl cis–trans isomerase NIMA-interacting 1 (PIN1), thus decreasing the ability of KLF10 to inhibit tumor progression." (PMID 34869587, 2021). "This work showed that RAF1 Ser338 phosphorylation, but not RAF1 kinase activity, is necessary to mediate this effect in cells and xenograft tumours treated with ionizing radiation." (PMID 33920182, 2021). "Sorafenib, by inhibiting RAF‐1 pathway, could promote apoptosis and sensitize HCC tumor cells to doxorubicin." (PMID 32841541, 2020). "This network demonstrates that 61 exosomal molecules may affect tumor progression through pathways controlled by key components including MET, Ras, RAF1, Mek, ERK1/2, MITF, BCL2, PI3K, Akt, mTOR, PD-1, KIT, JAK STAT3, or ETS1." (PMID 31681332, 2019). "Collectively, these findings indicate that targeting PAK1 by pharmacological inhibitor IPA-3 could suppress tumor growth and metastatic behavior of ESCC cells and that it likely acts through blocking the Raf1/MEK1/ERK signaling pathway." (PMID 30971268, 2019). "By reviewing the list of genes without impact like ERBB3, CASP8, RAF1 and KRAS (FaDu) as well as KEAP1, KRAS, RAF1 and FANCD2 (SAS), one finds tumor drivers ranked among the top 100 mutated genes in HNSCC." (PMID 29719593, 2018). "These genetic alterations involving BRAF, KRAS, RAF1, NF1, FGFR1, and FGFR2 were mutually exclusive (i.e. no tumor harbored any two of these variants simultaneously)." (PMID 29880043, 2018). "Regorafenib is a potent oral inhibitor of multiple kinases which might be involved in tumor angiogenesis (VEGFR-1, -2, -3, Tie-2), oncogenesis (KIT, RET, RAF-1, BRAF, BRAFV600E), and tumor niche formation (PGDFR, FGFR)." (PMID 29371921, 2017).
tumor (continued). "In contrast to RAF1, YAP1 protein levels were higher in tumours compared with the surrounding tissue, and the degree of YAP1 expression in tumours (ratio of YAP1 expression in matched tumour/non-tumour tissue) positively correlated with tumour grade." (PMID 28000790, 2016). "However, truncated and fusion RAF1 and BRAF transcripts have been found to occur in several cancer cell lines and tumor samples." (PMID 25473895, 2015). "Furthermore, miR-7 regulates expression of other molecules downstream of EGFR in a coordinate fashion, including RAF1, IRS1, IRS2, PAK1, supporting a tumor suppressor function for miR-7 in these and other cancers." (PMID 23115635, 2012). "However, analysis of matched pairs revealed a subgroup that showed significant increases in Raf-1 and MAPK levels in CRPC tumours." (PMID 21559022, 2011). "Furthermore, chromatin IP (ChIP) analysis of human NSCLC tumor samples demonstrated increased recruitment of E2F1 and Raf-1 to proliferative promoters like cdc6 and cdc25A." (PMID 19712465, 2009). "Regorafenib is a sorafenib-derived multi-kinase inhibitor that targets tumor cells and their microenvironment due to inhibition of angiogenic (VEGFR1-2 and TIE-2), stromal (PDGFRβ and FGFR1), oncogenic (RET and c-KIT), and intracellular (BRAF, c-RAF/Raf-1) kinases." (PMID 41154409, 2025). "Moreover, consistent with previous data, a higher level of RAF1 was displayed in OS tumor tissues compared with the adjacent non-cancer tissues." (PMID 39076089, 2024). "In tumour without BRAFV600E mutation, extensive screening is valuable to identify an alternative druggable genetic alteration of the MAPK pathway (e.g., gene fusion involving BRAF, RAF1, ALK, ROS1)." (PMID 36831464, 2023). "Previous studies have identified incomplete tumor “capsule” as an imaging marker for predicting MVI, postoperative extrahepatic metastasis, and high BRAF and RAF1 expression in HCC, and the latter could accelerate tumor proliferation and differentiation and promote tumor invasion and metastasis." (PMID 37191923, 2023). "In this study, lentivirus knockdown and overexpression of RAF1 were transfected into FADU and SCC15 cell lines, and it was proved that the downregulation of RAF1 could inhibit the proliferation, migration, invasion and promote apoptosis of tumor cells." (PMID 35668458, 2022). "One early activated URM is RAF1, a known oncogene but which is also capable of tumor suppressant activity related to decreased IL-6 and JAK/STAT3 signaling activity, and simultaneous IL-6 and STAT3 activation has been shown to promote tumor formation in gastrointestinal tissues." (PMID 34983392, 2022). "Interestingly, ablation of BRAF did not reproduce this tumour-protective effect, suggesting that it is due to a specific RAF1 function." (PMID 33920182, 2021). "Moreover, the increased protein levels of p-Raf-1, p-MEK1/2, p-ERK1/2, and cyclin A1 and the decreased protein level of p27 were also observed in six SiHa-HK2 or HeLa-HK2 cells derived xenografted tumor tissues, compared to their control groups (SiHa-GFP and HeLa-GFP, p<0.05)." (PMID 33324557, 2020). "Sorafenib is a multikinase inhibitor that can inhibit tumor cell proliferation and angiogenesis through the inactivation of vascular endothelial growth factor receptor (VEGFR), platelet-derived growth factor receptor (PDGFR), c-kit receptor, and the serine-threonine kinase Raf-1." (PMID 30781816, 2019). "Thus, Ras targeting is a critical factor for Raf-1 interaction, activation, MAPK signaling and cell transformation in vitro as well as tumor initiation in vivo; however, another determinant outside the Ras targeting domain is necessary for Ras-induced in vivo tumor progression." (PMID 27239960, 2016).
tumor (continued). "RAF1 expression in tumours was significantly lower compared with the matched surrounding non-tumour tissue, and the degree of RAF1 expression in tumour (defined as the ratio of RAF1 expression in matched tumour/non-tumour tissues) negatively correlated with tumour grade." (PMID 28000790, 2016). "To investigate this, we performed biochemical analysis of xenograft lysates, which confirmed RAF1 knockdown and recapitulated the increased expression of YAP1 and GP130 as well as the higher levels of STAT3 phosphorylation observed in the autochthonous tumours." (PMID 28000790, 2016). "The ERK activation status, on the other hand, did not correlate with proliferation in autochthonous tumours, xenografts, or cultured cells, implying that in the absence of RAF1 proliferative signalling is rewired to rely on the activation of YAP1 and STAT3 rather than ERK." (PMID 28000790, 2016). "RAF1 rearrangement was observed in ∼4.5% (3 out of 66) of PCa cases; PCA‐23 harbored RAF1 rearrangement, second case (PCA‐56) displayed 3' deletion and third case (PCA‐40) displayed 3' deletion in one tumor foci and RAF amplification and 5' deletion in another tumor foci." (PMID 25809148, 2015). "From the results presented here, it is evident that increasing levels of Raf-1 and/or MAPK are indicative of more rapid biochemical relapse and a more rapid decline into CRPC, which ultimately results in reduced survival times, with tumours showing more severe and aggressive action." (PMID 21559022, 2011). "Furthermore, this study provides new insight into the molecular mechanism of the anti-tumor selectivity of HDACIs and suggests that HDACIs might be a more effective clinical target in tumors with high c-Jun/Fra-1 activity mediated by MKK7 and Raf1." (PMID 26734995, 2016). "However, genetic alterations of Raf-1 in human tumours have not been found." (PMID 14735164, 2004). "It has been reported that ERK also phosphorylates the upstream proteins of its pathway, including neg receptor, SOS, Raf-1, and MEK, and then regulates the signaling pathway by its own negative feedback, participating in tumor regulation." (PMID 39620221, 2024). "Non-BRAF alterations were detected in four tumor samples consisting of CLIP2:NTRK2, KANK1:NTRK2, RAF1:QKI, and KRAS Q61H." (PMID 36163281, 2022). "In F/F tumour-bearing livers, ERK phosphorylation was observed in non-tumour, but not in tumour tissue; in Δp/np livers, ERK phosphorylation could also be detected in tumours, implying that RAF1 is dispensable for ERK activation under these conditions." (PMID 28000790, 2016). "Unlike current invasive pharmacodynamic assays which measure Raf-1 depletion and HSP70 induction, the measurement by (methyl-11C)choline does not require the biopsy sampling of tumours which can be problematic." (PMID 12232764, 2002). "Moreover, Spearman’s correlation analysis demonstrated that there was the negative correlation between expression of RAF1 and miR-431-5p in tumor tissues, and the positive correlation between expression of FBXL19-AS1 and RAF1 in tumor tissues (r = −0.231, r = 0.243, P<0.05)." (PMID 30610161, 2019).